RNU6-157P (RNA, U6 small nuclear 157, pseudogene)
Gene: Small nuclear RNA gene on chromosome 1 (172,366,540 to 172,366,646, forward strand). Ensembl gene ENSG00000206684.
Homologues: Orthologues: chimpanzee U6 (100% identical), macaque U6 (93% identical), dog U6 (78% identical), dog U6 (75% identical), dog U6 (73% identical), rabbit U6 (70% identical), mouse Gm56092 (63% identical). Paralogues in human: RNU6-589P (88% identical), RNU6-1316P (86% identical), RNU6-310P (86% identical), RNU6-1042P (85% identical), RNU6-1145P (85% identical), RNU6-761P (85% identical), RNU6-15P (84% identical), RNU6-20P (84% identical), RNU6-393P (84% identical), RNU6-44P (84% identical), RNU6-698P (84% identical), RNU6-723P (84% identical), and 1287 more.